FOXM1 (forkhead box M1)
Diseases named in the same sentence as FOXM1 in open-access papers (continued):
Sharing a sentence is not in itself a finding about the gene and the disease.
pancreatic cancer (125 papers, 2010 to 2026). "The involvement of FoxM1 in the TGF-β/Smad signaling pathway has been linked to pancreatic cancer progression; however, the mechanisms behind the cooperative regulation of TGF-β signaling by FoxM1 and Smad4 remain poorly understood." (PMID 41963301, 2026). "On this regard the ubiquitin-specific protease 5 (USP5) has been recently associated with pancreatic cancer tumorigenesis and progression for its role in extending the half-life of FOXM1 by reducing its endogenous ubiquitination." (PMID 35241126, 2022). "We found FOXM1 transcriptionally activated miR-552 expression and miR-552 is positively associated with pancreatic cancer metastasis." (PMID 33867818, 2021). "Loss of FoxM1 expression in pancreatic cancer suppresses cancer progression and metastasis in vitro and in vivo." (PMID 32429421, 2020). "Taken together, these data suggested that DOT1L‐induced H3K79me2 was associated with the regulation of FOXM1 in pancreatic cancer and colon cancer." (PMID 30628173, 2019). "With bioinformatics analysis, we suggested that DOT1L‐induced H3K79me2 is associated with FOXM1 regulation in pancreatic cancer and colon cancer." (PMID 30628173, 2019). "Elevated FOXM1 protein levels were associated with gemcitabine chemoresistance in patients with pancreatic cancer." (PMID 30782607, 2019). "We demonstrated that the FOXM1 expression is significantly associated with poor response to gemcitabine-based chemotherapy and a poor prognosis of advanced pancreatic cancer patients." (PMID 30782607, 2019). "In the present study, we investigated the association of FOXM1 expression and chemoresistance in pancreatic cancer." (PMID 30782607, 2019). "FOXM1 can cause resistance to apoptosis by activating nuclear factor κB (NF-κB) pathway in pancreatic cancer cell lines." (PMID 30782607, 2019). "Therefore, the anticancer effect of BF-B on human pancreatic cancer cells was investigated, and the underlying mechanism was explored, specifically focused on FoxM1 inhibition." (PMID 32429421, 2020). "In addition, our further data show that the expression levels of OPN and FOXM1 were significantly upregulated in pancreatic cancer tissues and were associated with poor clinical outcome." (PMID 30367545, 2019). "Several studies have demonstrated that the FOXM1 signaling network is frequently deregulated in human malignancies with leading to its overexpression, which is associated with poor prognosis for various cancers, including pancreatic cancer." (PMID 24325450, 2013). "A Fox member, FoxM1, is well-known to be associated with oncogenesis of pancreatic cancer." (PMID 20686608, 2010). "In this study, we utilized molecular cytology techniques, animal models, and human pancreatic cancer tissues to investigate the role of FoxM1 in Smad4 stabilization and its regulation of TGF-β signaling." (PMID 41963301, 2026). "Recently, several studies have shown that the transcriptional and post-translational regulation of LDHA by KLF4, FOXM1 and lysine-5 acetylation promotes aerobic glycolysis and the progression of pancreatic cancer." (PMID 39930542, 2025). "PRRX1, along with the cofactor FOXM1, was reported to activate the transcription of PRKDC, the gene encoding DNA-PKcs, in pancreatic cancer cells." (PMID 40114375, 2025). "Dysregulated expression of FOXM1 in pancreatic cancer substantially drives the progression of PDAC63, largely due to its role in regulating cell cycle and proliferation." (PMID 39897042, 2025). "As in lung cancer, pancreatic cancer cells are also positively regulated by the feedback loop between FOXM1 and hepatocyte growth factor (HGF)/MET signaling." (PMID 39594778, 2024).
pancreatic cancer (continued). "Contemporary investigations have showcased an up-regulated expression of FOXM1 across an array of malignancies, encompassing pancreatic tumors." (PMID 39022126, 2024). "Intriguingly, a previous study showed that DKK1 and FOXM1 can form a positive feedback loop that promotes cell growth in esophageal squamous cell carcinoma and pancreatic cancer." (PMID 39466790, 2024). "Inhibition of DOT1L reduced H3K79me2 enrichment at the FOXM1 promoter, thereby downregulating FOXM1 and promoting IL-12 production and DC maturation in colon and pancreatic cancers." (PMID 36627707, 2023). "FOXM1 expression has been found to be elevated in various malignancies, such as liver, breast, prostate, and pancreas cancers, as well as others." (PMID 37526082, 2023). "FOXM1, is a transcription factor with several functions, that has been reported to play a critical role in pancreatic cancer." (PMID 35241126, 2022). "Expression of FOXM1 is significantly elevated in many human tumors, including non-small cell lung cancer, breast cancer, basal cell carcinoma, hepatocellular carcinoma, pancreatic cancer, prostate cancer, colon cancer, medulloblastoma and GBM9–13." (PMID 35978012, 2022). "Recently, the transcriptional factor FOXM1 has been found at elevated levels in patients with a bad prognosis in a multitude of malignancies, including pancreatic cancer." (PMID 35241126, 2022). "A previous study showed that FOXM1 promotes the Warburg effect and pancreatic cancer progression via transactivation of LDHA expression." (PMID 35789607, 2022). "Other articles demonstrated that ATX is the downstream transcription target gene of FOXM1, and ATX can promote FOXM1 expression by inhibiting the Hippo signaling pathway, thereby promoting the progression of pancreatic cancer." (PMID 35651786, 2022). "For example, overexpression of USP5 was shown to stabilise FoxM1, a protein with a key role in tumorigenesis and progression of pancreatic cancers." (PMID 35895711, 2022). "In prostate cancer, HIF-1α induced an increased expression of Forkhead box M1 (FoxM1) by binding to its promoter, while in pancreatic cancer, HIF-1α promoted PAFAH1B2 expression." (PMID 35745656, 2022). "In line with our report, FOXM1 upregulation is critical in the initiation, advancement, and diversion of pancreatic cancer." (PMID 36292640, 2022). "TPP+-containing mitochondria-targeting agents (e.g., Mito-metformin) inhibit pancreatic cancer cell proliferation via downregulation of the Akt/FOXO3/FOXM1 signaling axis in pancreatic cancer cells." (PMID 35756631, 2022). "Growing evidence has demonstrated that FOXM1 is frequently overexpressed in breast cancer, lung cancer, hepatocellular carcinoma, glioblastoma and pancreatic cancer." (PMID 33867818, 2021). "FOXM1 promotes EMT in pancreatic cancer by directly binding to the promoter region of the caveolin-1 gene and promoting its expression." (PMID 33428593, 2021). "In summary, this study provides mechanistic evidence for a tumorigenic role of miR-552 in pancreatic cancer and uncovers a novel FOXM1-miR-552-DACH1/PCDH10/SMAD4 axis that promotes pancreatic cancer progression." (PMID 33867818, 2021). "To find out FOXM1-induced abnormal miRNAs in pancreatic cancer, we analyzed TCGA database and figured out miR-552 as the most relevant miRNA with FOXM1." (PMID 33867818, 2021). "In pancreatic cancer, FOXM1 expression was upregulated in a glucose-dependent manner, which correlated with epithelial-to-mesenchymal transition (EMT) in pancreatic cancer cell lines." (PMID 34205406, 2021). "Further investigation revealed that FOXM1 binds directly to the LDHA promoter to promote its expression in pancreatic cancer cells." (PMID 34205406, 2021). "USP5 promotes tumorigenesis of pancreatic cancer cells by stabilising the FoxM1 protein, which is a substrate of FBXW7." (PMID 33658627, 2021).
pancreatic cancer (continued). "Taken together, our findings provide a new FOXM1-miR-552-DACH1/PCDH10/SMAD4 axis to regulate pancreatic cancer cell progression and new opportunities for therapeutic intervention against this disease." (PMID 33867818, 2021). "In pancreatic cancer, FOXM1 promotes aerobic glycolysis and progression by binding directly to the LDHA promoter region and regulating the expression of the LDHA gene." (PMID 34740322, 2021). "In pancreatic cancer cells, down-regulation of FoxM1 reduced the expression of MMP-2 and MMP-9, resulting in the inhibition of migration and invasion." (PMID 32429421, 2020). "Accordingly, PANC-1 cells were used to study the anti-pancreatic cancer activity of BF-B, as an inhibitor of FoxM1 expression." (PMID 32429421, 2020). "Our previous study identified five FOXM1 isoforms present in pancreatic cancer, among which FOXM1c was predominantly expressed and significantly drive PDAC malignant progression." (PMID 33298873, 2020). "In pancreatic cancer, integrin αvβ3 interacted with osteopontin on pancreatic stellate cells, which led to the activation of αvβ3-Akt/Erk-FOXM1 (forkhead box protein M1) cascade and promoted CSC-like properties of pancreatic cancer." (PMID 33041823, 2020). "OPN promotes the epithelial mesenchymal transition (EMT) and cancer stem cells (CSC) like properties of pancreatic cancer cells (PCCs) by activating the integrin αvβ3/Akt/Erk/FOXM1 cascade in a paracrine manner." (PMID 33680951, 2020). "Deubiquitination of FOXM1 by UCHL3 was also shown to promote pancreatic cancer progression and gemcitabine resistance." (PMID 33680951, 2020). "Integrin αvβ3 receptor activation by osteopontin (OPN) has been found to upregulate FOXM1 expression in pancreatic cancer cells." (PMID 33680951, 2020). "Hypoxia-driven phosphorylated glycoprotein such as osteopontin, promoted stem cell-like properties and EMT in pancreatic cancer cells in a paracrine manner, through integrin αvβ3-Akt/Erk- forkhead box protein M1 (FOXM1) signaling." (PMID 33330442, 2020). "In the present study, we used immunohistochemical staining for investigating the relation between FOXM1 protein expression and resistance toward gemcitabine-based chemotherapy in patients with pancreatic cancer." (PMID 30782607, 2019). "Fortunately, IFNγ can sensitize pancreatic cancer cells to gemcitabine via the STAT1/FOXM1/NFκB axis." (PMID 30782607, 2019). "Our results suggest that the STAT1/FOXM1/NFκB axis can inhibit chemotherapy resistance in pancreatic cancer." (PMID 30782607, 2019). "In the present study, we found that elevated expression of FOXM1 promoted the resistance of pancreatic cancer cells to gemcitabine." (PMID 30782607, 2019). "Our work revealed that tumor‐conditioned medium inhibits BMDC maturation via upregulation of H3K79me2 on the FOXM1 promoter, which increases FOXM1 expression in pancreatic cancer and colon cancer." (PMID 30628173, 2019). "Previous studies have shown that FOXM1 is essential for pancreatic cancer cells growth and survival." (PMID 30782607, 2019). "We found that only the expression of disruptor of telomeric silencing 1‐like (DOT1L), the sole enzyme that specificity mediates H3K79 methylation, correlated with FOXM1 in both pancreatic cancer and colon cancer tissue." (PMID 30628173, 2019).
pancreatic cancer (continued). "Accumulating evidence has suggested that aberrant expression of FOXM1 contributes to the carcinogenesis and progression of pancreatic cancer." (PMID 30367545, 2019). "To support our in vitro observations, we retrospectively investigated the clinical value of OPN and FOXM1 expression in pancreatic cancer patients by IHC." (PMID 30367545, 2019). "In pancreatic cancer cells treated with gemcitabine, FOXM1 affected nuclear factor κB (NF-κB) signaling activity." (PMID 30782607, 2019). "First, the expression levels of OPN and FOXM1 were assessed in 75 pancreatic cancer tissues and 25 normal pancreatic tissues by IHC." (PMID 30367545, 2019). "In this study, we observed that the level of pSTAT1 was negatively correlated with the level of FOXM1 in pancreatic cancer tissue samples." (PMID 30782607, 2019). "Aberrant expression of FOXM1 has been observed in the majority of human solid tumors, including pancreatic cancer." (PMID 30367545, 2019). "First, we investigated the levels of FOXM1 in 93 human pancreatic cancer tissue samples using immunohistochemical analysis; all these patients received gemcitabine-based monotherapy (n=57, 61.3%) or combined chemotherapy (n=36, 38.7%)." (PMID 30782607, 2019). "In gemcitabine resistance cell line models of pancreatic cancer, FOXM1 expression increased, which induced gemcitabine chemoresistance in vitro." (PMID 30782607, 2019). "Taken together, these results indicated that the IFNγ/STAT1 pathway suppressed FOXM1 transcription directly in pancreatic cancer cells." (PMID 30782607, 2019). "To further assess the effect of FOXM1 on the sensitivity of pancreatic cancer cells to chemotherapy, we generated human pancreatic cancer cells that overexpressed FOXM1 (BxPC3-FOXM1) and cells in which FOXM1 had been knocked out by CRISPR/Cas9 (SW1990-KO)." (PMID 30782607, 2019). "Since FoxM1 was previously identified as regulator of glycolytic genes in pancreatic cancer, we further investigated the correlation between FOXM1 and glycolytic genes expression." (PMID 30873387, 2019). "Based on our preliminary in vitro data, we further explored the clinical value of OPN and FOXM1 in pancreatic cancer patients." (PMID 30367545, 2019). "In our study, we used patients’ tissue, PDX models, and cell lines to confirm that overexpressed FOXM1 suggests pancreatic cancer resistance to gemcitabine." (PMID 30782607, 2019). "In the present study, we found that pancreatic cancer patients with elevated FOXM1 expression has a poor prognosis and poor response to gemcitabine-based chemotherapy." (PMID 30782607, 2019). "Dysregulated FOXM1 signaling has been identified in a wide range of cancers including pancreatic cancer, and this dysregulation is considered as a key regulator of EMT and CSC‐like properties." (PMID 30367545, 2019). "The 37 cases of pancreatic cancer were then divided into groups with high or low levels of pSTAT1 and FOXM1." (PMID 30782607, 2019). "According to the results derived from GEPIA, we observed that the expression levels of OPN and FOXM1 were significantly upregulated in pancreatic cancer tissues compared to normal pancreatic tissues." (PMID 30367545, 2019). "In pancreatic tumors and cancer cell lines, FOXM1 and LDHA were found to be overexpressed; increased expression of FOXM1 upregulated LDHA activity and expression at both mRNA and protein level." (PMID 31146503, 2019). "As FOXM1 was overexpressed in pancreatic cancer and colon cancer, we focused on the H3K4me3, H3K36me3, and H3K79me2 modifications of FOXM1." (PMID 30628173, 2019). "Most pancreatic cancer patients’ samples were positive for FOXM1 expression, only 25 cases (26.9%) were low." (PMID 30782607, 2019). "It was found that all pancreatic cancer cell lines exhibited higher levels of FOXM1 expression and resistance to gemcitabine than normal pancreatic ductal epithelial cells." (PMID 30782607, 2019).
pancreatic cancer (continued). "As for FOXM1, intense staining was detected in the cytoplasm and nucleus of tumor cells in pancreatic cancer tissues, and cells exhibited a predominantly nuclear localization pattern." (PMID 30367545, 2019). "In this study, we showed that FOXM1 is a suppressor of BMDC maturation in pancreatic cancer and colon cancer." (PMID 30628173, 2019). "Studies have found that downregulation of FoxM1 in pancreatic cancer cells reduced the expression of MMP-2 and MMP-9, thereby inhibiting pancreatic cancer cell migration and invasion." (PMID 30580327, 2018). "In pancreatic cancer cells FoxM1 participates in Warburg effect by stimulating expression of LDHA31." (PMID 28387346, 2017). "Recently, FOXM1 was found to regulate glucose metabolism in pancreatic cancer via transactivation of LDHA expression." (PMID 27351131, 2016). "A previous report showed that FOXM1 played important roles in reprogramming of glucose metabolism in pancreatic cancer via transcriptional regulation of LDHA expression." (PMID 27351131, 2016). "We first performed a qRT-PCR analysis of the FOXM1 expression in 13 malignant melanoma cell lines, NHEMs and a human pancreatic cancer cell line, PANC1, as a positive control." (PMID 26640950, 2015). "The abnormal upregulation of FOXM1 is involved in the oncogenesis of various human cancers, including breast, lung, bile duct, prostate, brain and pancreatic cancers, in addition to basal cell carcinoma (BCC) and head and neck squamous cell carcinoma (SCC)." (PMID 26640950, 2015). "A previous study has shown that over-expression of FOXM1 is responsible for EMT phenotype in pancreatic cancer cells, which is in part mediated through the regulation of MiR-200b." (PMID 24918286, 2014). "Equally important would be to address the pancreatic cancer specific questions like desmoplasia using the available tissue-specific FOXM1 knockout models of FOXM1." (PMID 24325450, 2013). "Further studies of the cross-talk of FOXM1 with other signaling pathways as well as studies of the CSC niche also would provide valuable insight into pancreatic cancer pathogenesis and lead to more preventive and therapeutic approaches for PDAC." (PMID 24325450, 2013). "In this review, we briefly describe the crucial role of FOXM1 in PCSCs in pancreatic cancer development and progression with a focus on recent insight into the cross-talk between FOXM1 and signaling pathways in PCSCs here and below." (PMID 24325450, 2013). "Forced overexpression of FOXM1 led to increased self-renewal capacity of AsPC-1 human pancreatic cancer cells, which was consistent with enhanced expression of CSC cell surface markers such as CD33 and EpCAM." (PMID 24325450, 2013). "Other evidence has shown that suppression of FOXM1 leads to a reduction in MMP-2 and MMP-9 expression levels in pancreatic cancer cells, which is associated with an overall decrease in cancer cell migration, invasion and angiogenesis." (PMID 23229761, 2013). "Recent studies using human and mammalian models revealed that FOXM1 has a role in promotion of tumorigenesis by stimulating stem cell-like characteristics in pancreatic cancer cells, including self-renewal capacity." (PMID 24325450, 2013). "Down-regulation of another member of this family, FOXM1 is known to be inhibiting proliferation, migration, and invasion of pancreatic cancer cells while up-regulation favours an EMT phenotype." (PMID 23152778, 2012). "Additionally, miR-320b has been shown to inhibit pancreatic cancer cell proliferation by directly targeting FOXM1." (PMID 41004495, 2025). "Given this background, it is intriguing to explore whether FOXM1 regulates CKS1B in pancreatic cancer, potentially contributing to the malignant phenotype of PDAC." (PMID 39897042, 2025). "Suppression of FOXM1 expression in pancreatic cancer cells suppresses VEGF secretion." (PMID 39594778, 2024). "A recent report showed that OTUB1 could accelerate metastasis of pancreatic cancer by inhibiting FOXM1 degradation." (PMID 38653740, 2024).